PLAAT3 (phospholipase A and acyltransferase 3)
Description:
Exhibits both phospholipase A1/2 and acyltransferase activities. Shows phospholipase A1 (PLA1) and A2 (PLA2) activity, catalyzing the calcium-independent release of fatty acids from the sn-1 or sn-2 position of glycerophospholipids. For most substrates, PLA1 activity is much higher than PLA2 activity. Shows O-acyltransferase activity,catalyzing the transfer of a fatty acyl group from glycerophospholipid to the hydroxyl group of lysophospholipid. Shows N-acyltransferase activity, catalyzing the calcium-independent transfer of a fatty acyl group at the sn-1 position of phosphatidylcholine (PC) and other glycerophospholipids to the primary amine of phosphatidylethanolamine (PE), forming N-acylphosphatidylethanolamine (NAPE), which serves as precursor for N-acylethanolamines (NAEs). Exhibits high N-acyltransferase activity and low phospholipase A1/2 activity. Required for complete organelle rupture and degradation that occur during eye lens terminal differentiation, when fiber cells that compose the lens degrade all membrane-bound organelles in order to provide lens with transparency to allow the passage of light. Organelle membrane degradation is probably catalyzed by the phospholipase activity (By similarity). (Microbial infection) Acts as a host factor for picornaviruses: required during early infection to promote viral genome release into the cytoplasm. May act as a cellular sensor of membrane damage at sites of virus entry, which relocalizes to sites of membrane rupture upon virus unfection. Facilitates safe passage of the RNA away from LGALS8, enabling viral genome translation by host ribosome. May also be involved in initiating pore formation, increasing pore size or in maintaining pores for genome delivery. The lipid-modifying enzyme activity is required for this process.
Synonyms: AdPLA; H-REV107; HREV107-1; HRSL3; HRASLS3; HREV107; PLA2G16; H-REV107-1; HREV107-3; MGC118754.; PLAAT-3; FPLD9
Tractability: Small molecule: a structure with a bound ligand is known; a high-quality ligand is known; it has a high-quality binding pocket. Antibody: UniProt places it where antibodies can reach, with medium confidence; UniProt predicts a signal peptide or a membrane-spanning region; its Gene Ontology location is reachable by antibodies, with medium confidence. PROTAC: ubiquitination databases record sites on it; a small molecule that binds it is known.
Target class: Enzyme; Hydrolase
Gene: Protein-coding gene on chromosome 11 (63,573,172 to 63,616,883, reverse strand). Ensembl gene ENSG00000176485.
Subcellular location: Cell membrane; Cytoplasm; Cytoplasm, cytosol; Cytoplasm, perinuclear region; Peroxisome membrane; Mitochondrion membrane; Nucleus envelope; Lysosome membrane; Endoplasmic reticulum membrane
Subcellular location (Human Protein Atlas): Mitochondria; Cytosol
Pathways (Reactome):
Metabolism: Acyl chain remodelling of PC; Acyl chain remodelling of PE; Acyl chain remodelling of PI; Acyl chain remodelling of PS
Gene Ontology:
Molecular function: acyltransferase activity, transferring groups other than amino-acyl groups; lipid binding; phospholipase A1 activity; phospholipase A2 activity; protein binding; acyltransferase activity; phospholipase activity
Biological process: N-acylphosphatidylethanolamine metabolic process; phospholipid metabolic process; ether lipid metabolic process; lens fiber cell differentiation; lipid catabolic process; membrane disassembly; organelle disassembly; peroxisome organization; phosphatidylethanolamine acyl-chain remodeling; regulation of adipose tissue development; triglyceride metabolic process; phospholipid biosynthetic process
Cellular component: cytoplasm; cytosol; endoplasmic reticulum; endoplasmic reticulum membrane; lysosomal membrane; lysosome; mitochondrial membrane; mitochondrion; nuclear envelope; peroxisomal membrane; peroxisome; plasma membrane; perinuclear region of cytoplasm
Genetic constraint (gnomAD): Loss-of-function variants: 13 observed, 10.37 expected, observed/expected ratio (o/e) 1.25, 90% interval 0.81 to 1.84. The upper end of that interval is the gene's LOEUF score, 1.84, which puts it in group 6 of 6, group 1 being the genes least tolerant of losing a copy. Missense variants: 142 observed, 147.76 expected, observed/expected ratio (o/e) 0.96, 90% interval 0.84 to 1.11. Synonymous variants: 52 observed, 61.92 expected, observed/expected ratio (o/e) 0.84, 90% interval 0.67 to 1.06.
Homologues: Orthologues: chimpanzee PLAAT3 (98% identical), guinea pig PLAAT3 (85% identical), pig PLAAT3 (85% identical), mouse Plaat3 (83% identical), rat Plaat3 (81% identical), rabbit PLAAT3 (80% identical), dog PLAAT3 (68% identical), zebrafish lratb.2 (30% identical). Paralogues in human: PLAAT2 (68% identical), PLAAT4 (49% identical), PLAAT5 (47% identical), PLAAT1 (46% identical), LRAT (28% identical), LRATD2 (28% identical), LRATD1 (23% identical).
Diseases named in the same sentence as PLAAT3 in open-access papers:
PLAAT3 is named in the same sentence as 42 diseases in open-access papers, as found by Europe PMC text mining. Sharing a sentence is not in itself a finding about the gene and the disease. The quoted sentences say what the papers report.
Obesity (7 papers, 2015 to 2023). Accumulation of substantial excess body fat. "Plaat3’s absence or divergence outside of mammals is also noteworthy, as it plays vital roles in obesity, cancer invasion, and vitamin A storage." (PMID 38168154, 2023).
pancreatic cancer (3 papers, 2020 to 2025). "Another way that KLF5 promotes glycolysis of pancreatic cancer is through transcriptional activation of phospholipase A and acyltransferase 3 (PLA2G16)." (PMID 37239940, 2023).
virus infection (3 papers, 2021 to 2025). "In this context, the quality control of organelles by PLAAT3 may also be associated with virus infection, where the inactivation of PLAAT3 in mammalian cells results in resistance to picornavirus infection." (PMID 40244184, 2025).
Insulin resistance (2 papers, 2021 to 2024). Increased resistance towards insulin, that is, diminished effectiveness of insulin in reducing blood glucose levels. "Phospholipase A/acyltransferase 3 (PLAAT3) inactivation has been linked to insulin resistance and reduced adipocyte differentiation via the PPARγ signaling pathway in human adipose stem cells." (PMID 39684239, 2024).
dyslipidemia (1 paper, 2024). "It is possible that AAJ management of dyslipidemia might not be through the regulation of Acly and Plaat3, as the tested gene transcriptions did not change significantly in the AAJ-treated groups." (PMID 38338541, 2024).
leukaemia (1 paper, 2025). "To test the relevance of the human orthologue PLAAT3 in leukaemia, we analysed PLAAT3 expression of ALL patients and observed an insignificant trend of worse overall survival in patients with increased PLAAT3 expression." (PMID 39642167, 2025).
lipodystrophy (1 paper, 2025). A congenital or acquired disorder characterized by abnormal loss or redistribution of the adipose tissue in the body. "The phenotypes observed in Plaat3−/− mice, i.e., low adiposity with the ectopic accumulation of hepatic fat and increased insulin resistance, are representative of the typical features of lipodystrophy." (PMID 40244184, 2025).
medulloblastoma (1 paper, 2023). A malignant, invasive embryonal neoplasm arising from the cerebellum. "Of these seven genes (LTBP1, MAP1A, MBNL2, LGALS1, PNRC1, DAB2, and PLAAT3), only one, LGALS1, had been researched previously in relation to medulloblastoma, where it is up-regulated in MBSHH patients and activated by the SHH signalling pathway." (PMID 36831428, 2023).
testicular cancer (1 paper, 2023). A primary or metastatic malignant neoplasm that affects the testis. "It is interesting to note that H-REV107/PLA2G16/PLAAT3, a representative member of the PLAAT family, also inhibits migration and invasion of NT2/D1 testicular cancer cells by targeting at PTGDS." (PMID 37063830, 2023).
tumor (20 papers, 2009 to 2025). "In summary, our functional analysis of PLAAT3 and Ly6A showed that their expression is upregulated in tumour cells co-cultured with NK cells in an IFN-γ-dependent manner." (PMID 39642167, 2025). "Most strikingly, our analysis revealed a seven-gene drug-tolerant signature in all four drug-tolerant cell lines, irrespective of chemotherapeutic treatment, parental cell line and tumour subgroup—LTBP1, MAP1A, MBNL2, LGALS1, PNRC1, DAB2 and PLAAT3." (PMID 36831428, 2023). "Examples of genes with more expression per cell in the erlotinib-treated group are PLAAT3, LCN2, CEBPD, and SAA1; conversely, LDHB is shown as an example for transcripts more abundant in control tumor cells." (PMID 36482068, 2022).
cancer (10 papers, 2015 to 2025). A tumor composed of atypical neoplastic, often pleomorphic cells that invade other tissues. "Second, constitutive expression of PLAAT3 in cancer cells induces cell death." (PMID 35906209, 2022).
infection (5 papers, 2019 to 2025). The state of being infected such as from the introduction of a foreign agent such as serum, vaccine, antigenic substance or organism. "For example, PLAAT3 (also known as PLA2G16) causes membrane rupture of endo-lysosomes to release the viral genomes upon infection with picornavirus and acts as a switch in virus entry and clearance." (PMID 36172355, 2022). "Upon picornavirus (e.g., coxsackievirus and rhinovirus) infection, the host lipid‐modifying enzyme PLAAT3/PLA2G16 promotes the delivery of the single‐stranded RNA viral genome to the cytosol before autophagy‐dependent degradation." (PMID 34459017, 2021).
PLAAT3 also shares sentences with these, for which no sentence is quoted: osteosarcoma (10 papers); breast carcinoma (9); non-small cell lung carcinoma (4); prostate carcinoma (3); enterovirus infection (2); pancreatic adenocarcinoma (2); rectum cancer (2); allergic asthma (1); anemia (1); asthma (1); breast tumor (1); cataract (1); colon carcinoma (1); colorectal cancer (1); eosinophilic esophagitis (1); gastric cancer (1); HIV-associated neurocognitive disorder (1); hyperlipidemia (1); lung fibrosis (1); lymph node metastasis (1); metabolic disorder (1); metastasis (1); metastatic tumors (1); Moyamoya disease (1); nasopharyngeal carcinoma (1); pancreatitis (1); prostate tumor (1); renal angiomyolipomas (1); schizophrenia (1); triple-negative breast carcinoma (1).